PRMT1 (protein arginine methyltransferase 1)
Diseases named in the same sentence as PRMT1 in open-access papers (continued):
Sharing a sentence is not in itself a finding about the gene and the disease.
gastric cancer (11 papers, 2017 to 2025). A primary or metastatic malignant neoplasm involving the stomach. "Wang and colleagues reported that PRMT1 abrogation and inhibition caused a suppression in gastric cancer cell proliferation, tumorigenesis, migration, and invasion." (PMID 40001488, 2025). "PRMT1 expression is associated with poor prognosis in gastric cancer patients and has been observed to be significantly upregulated in non-small cell lung carcinoma." (PMID 29868478, 2018). "However, in gastric cancer, low expression of PRMT1 is associated with poor prognosis." (PMID 29383172, 2017). "In conclusion, our study identifies a novel mechanism by which PRMT1-mediated methylation of NUSAP1 promotes 5-FU resistance in gastric cancer by stabilizing Notch2." (PMID 40393971, 2025). "Given our ongoing research on the role of arginine methylation in gastric cancer, we analyzed the expression of PRMT1 and PRMT5 in gastric cancer patients and found that their high expression was associated with poor prognosis." (PMID 40393971, 2025). "The results of the comet assay showed that after knockdown of PRMT1, DNA damage in gastric cancer cells increased." (PMID 40858547, 2025). "We further identified multiple arginine methylation sites on NUSAP1 and demonstrated that PRMT1-mediated R422me2 modification facilitates its interaction with Notch2, stabilizing Notch2 protein expression and promoting 5-FU resistance in gastric cancer cells." (PMID 40393971, 2025). "Bioinformatics analysis revealed significantly upregulated PRMT1 expression in gastric cancer tissue compared to normal tissue." (PMID 38326807, 2024). "Following AMI-1 treatment, PRMT1-mediated proliferation of gastric cancer cells was inhibited, exhibiting a dose-dependent effect." (PMID 38326807, 2024). "Nevertheless, the protective effect of PRMT1 has been suggested in patients with gastric carcinomas, positively affecting survival and recurrence rates, especially in patients treated with adjuvant therapy." (PMID 31655611, 2019). "To investigate the effects of PRMT1 methyltransferase activity and macrophage polarization on gastric cancer progression in vivo, we conducted experiments using the PRMT1 enzymatic activity inhibitor MS023 and the macrophage-depleting agent clodronate liposomes." (PMID 40858547, 2025). "Here, we found upregulation of PRMT1 in patient tissues and established human gastric cancer cells." (PMID 37564212, 2023). "PRMT1 expression is also associated with poor prognosis in breast and gastric cancers, though no study has fully addressed the clinical relevance and function of PRMT1 in HCC." (PMID 29383172, 2017). "In gastric cancer (GC), increased expression levels of PRMT1 correlate with augmented proliferative and metastatic capabilities of GC cells." (PMID 41256732, 2025). "Our previous studies have shown that PRMT1 and PRMT4/CARM1 promote gastric cancer proliferation and metastasis, underscoring the significance of NUSAP1 interactions with PRMT1 and PRMT5." (PMID 40393971, 2025). "PRMT1 also plays a role in promoting the EMT process through the Hippo signaling pathway and enhances the migration and invasive ability of gastric cancer cells." (PMID 38326807, 2024). "It is worth noting that PRMT1 exhibits a dual role, as it not only promotes the EMT process but also inhibits the proliferation of gastric cancer cells." (PMID 38326807, 2024).
glioblastoma (11 papers, 2015 to 2025). The most malignant astrocytic tumor (WHO grade IV). "A promising target is PRMT1 because it is overexpressed in glioblastoma." (PMID 33440687, 2021). "PRMT1 can methylate MYC in myeloid and glioblastoma cells and modulate its transcriptional activity." (PMID 37310381, 2023). "PRMT1 is also a known contributor to the development of glioblastoma (GBM)." (PMID 33440687, 2021). "Our study demonstrates that TRIM25 promotes glioblastoma cell growth and invasion by regulating the PRMT1/c-MYC pathway through mediation of the splicing factor NONO." (PMID 38303029, 2024). "PRMT1 and PRMT5 regulate the EGFR signaling pathway by methylating EGFR (in colorectal and TNBC cells), or by methylating histones on the EGFR promoter (in glioblastoma or colorectal cells) to regulate its transcription." (PMID 35053470, 2022).
non-small cell lung carcinoma (11 papers, 2015 to 2024). A group of at least three distinct histological types of lung cancer, including non-small cell squamous cell carcinoma, adenocarcinoma, and large cell carcinoma. "Non-small-cell lung cancer (NSCLC) patients become resistant to targeted therapies such as tyrosine kinase inhibitors (TKIs) through mutations in the EGFR gene and by overexpression of proteins such as p120-catenin and PRMT-1." (PMID 37444572, 2023). "To evaluate this hypothesis, we knocked down PRMT1 expression in A549 human non-small cell lung cancer cells that express high levels of PRMT1, and examined phosphorylation levels of histone H3 at serine 10, which is known as a substrate of AURKB." (PMID 26460953, 2015). "A recent investigation showed that PRMT1 regulated EMT by methylating Twist1 at the arginine residue 34, which is required for E-cadherin repression in non-small cell lung cancer cells." (PMID 26813495, 2016). "Moreover, PRMT1 can methylate the inner centromere protein (INCENP) at R887 to favor its interaction and the subsequent activation of aurora kinase B in A549 non-small cell lung cancer cells." (PMID 34833023, 2021). "Since mitochondrial Ca2+ uptake is essential for mitochondrial metabolic activity, we manipulated the expression of PRMT1 and UCP2, proteins known to affect the mitochondrial Ca2+ uptake machinery, to investigate their effect on human non-small-cell lung cancer cell lines A549, Calu-3 and H1299." (PMID 29113301, 2017).
ovarian carcinoma (11 papers, 2018 to 2025). A malignant neoplasm originating from the surface ovarian epithelium. "Another research in ovarian cancer found that PRMT1-mediated BRD4-ADMA modification is associated with TGF-β signaling and promotes metastasis and invasion." (PMID 40612681, 2025). "Targeting PRMT1-mediated arginine methylation may provide a novel diagnostic target and an effective therapeutic strategy for ovarian cancer treatment." (PMID 37737256, 2023). "However, in BRD4-R3K mutant cells and deficiency of PRMT1, the metastasis was inhibited in ovarian cancer cells." (PMID 37737256, 2023). "Interestingly, in ovarian carcinomas, upregulation of PRMT1 expression is associated with an increased methylation of the apoptosis signal-regulated kinase 1 (ASK1), which confers tumor cells with resistance to platinum-based chemotherapeutic agents." (PMID 34833023, 2021). "Pharmacological inhibition of PRMT1 has been demonstrated to reduce ovarian cancer proliferation, migration, and invasion both in vivo and in vitro." (PMID 39908270, 2025). "PRMT1 is highly expressed in ovarian cancer and is known to facilitate the methylation of bromodomain-containing protein 4 (BRD4), which is crucial for both early embryonic development and cancer progression." (PMID 39908270, 2025). "To assess the clinical significance of our findings, we performed an IHC analysis of tissue microarray in ovarian cancer using anti-PRMT1 and anti-BRD4 antibodies." (PMID 37737256, 2023). "Our results indicate that arginine methylation of BRD4 by PRMT1 is involved in ovarian cancer tumorigenesis." (PMID 37737256, 2023). "Multiple approaches were used to explore the mechanism of PRMT1-mediated BRD4 methylation and to determine the biological functions of BRD4 and PRMT1 in ovarian cancer." (PMID 37737256, 2023). "In the present work, we found that PRMT1 was overexpressed in ovarian cancer tissues, and high expression of PRMT1 was correlated to poor clinical outcomes in ovarian cancer patients." (PMID 37737256, 2023). "PRMT1 is overexpressed in ovarian cancer tissue and is a potential marker for poor prognosis in ovarian cancer patients." (PMID 37737256, 2023). "AMI-1, the specific inhibitor of PRMT1, significantly reduced the cell proliferation of ovarian cancer and abolished the BRD4-ADMA modification in ovarian cancer." (PMID 37737256, 2023). "Silencing of PRMT1 inhibited ovarian cancer proliferation, migration, and invasion in vivo and in vitro." (PMID 37737256, 2023). "Knockdown of PRMT1 profoundly blocked the proliferative activities in ovarian cancer cells, as analyzed by colony formation assay, CCK-8 assay, cell proliferation." (PMID 37737256, 2023). "PRMT1 was overexpressed in ovarian cancer tissues and promoted ovarian cancer progression, which was correlated to poor clinical outcomes." (PMID 37737256, 2023). "More recently, in ovarian cancer cells, it was shown that PRMT1 can be phosphorylated by DNA-PK in response to cisplatin, thus inducing its recruitment on chromatin and its enzymatic activity towards H4R3." (PMID 34833023, 2021). "It has been shown that FAM98A, a new substrate of PRMT1, is expressed in ovarian cancer cell lines and is correlated with migration and invasion of ovarian cancer cells." (PMID 30064416, 2018). "Knock-down of PRMT1 suppresses proliferation, migration, invasion, as well as colony formation of ovarian cancer cells." (PMID 30064416, 2018). "Cervical and ovarian cancer patients with lower PRMT1 levels were likely to benefit more from cisplatin-based chemotherapy and had a longer overall survival period when compared to the patients with high PRMT1 expression." (PMID 39703687, 2024). "Indeed, the downregulation of PRMT1 in both cervical cancer and ovarian cancer cells improved their sensitivity to cisplatin treatment." (PMID 39703687, 2024). "PRMT1 has also been identified as an oncogene in ovarian cancer." (PMID 38326807, 2024).
ovarian carcinoma (continued). "PRMT1 also acts as a protective factor against cisplatin-induced apoptosis in ovarian cancer cells." (PMID 38326807, 2024). "In comparison to tumors derived from ovarian cancer A2780 cells, those cells with stable knockdown of PRMT1 using the shRNA approach exhibited sharply decreased tumor growth as well as reduced tumor weight, implying that depletion of PRMT1 attenuated ovarian tumor growth." (PMID 37737256, 2023). "Taken together, our findings may provide a basis for the development of a potential therapeutic strategy by targeting PRMT1-mediated asymmetric arginine methylation for ovarian cancer treatment." (PMID 37737256, 2023). "Additionally, in vivo and in vitro experiments proved that PRMT1 enhanced ovarian cancer cell proliferation and ovarian cancer tumorigenesis." (PMID 37737256, 2023). "PRMT1 arginine methylation controlled the response to cisplatin in ovarian cancer cells." (PMID 37737256, 2023). "In vitro experiment was performed to examine the functions of PRMT1 in ovarian cancer cells." (PMID 37737256, 2023). "PRMT1 was also reported to be involved in ovarian cancer cisplatin." (PMID 37737256, 2023). "The abnormal expression level of PRMT1 has been seen with various cancer types such as lung, breast, prostate, colon, gastric, bladder, lymphoma, and glioma cancers, and it has been suggested that PRMT1 is critical for the development of ovarian carcinoma." (PMID 34066975, 2021). "Abnormal expression of PRMT1 has been seen with breast and prostate cancer, and may have a role in the progression of ovarian carcinoma." (PMID 30064416, 2018). "Moreover, we disclose that asymmetric methylation by PRMT1 was required for BRD4 phosphorylation and BRD4-induced ovarian cancer cell migration and invasion, which may be associated with transforming growth factor-β (TGF-β) signaling." (PMID 37737256, 2023). "Our results suggest that PRMT1 may exert its oncogenic roles in ovarian cancer." (PMID 37737256, 2023). "Therefore, therapeutic targeting of PRMT1-mediated arginine methylation may be a promising strategy for ovarian cancer treatment." (PMID 37737256, 2023). "Notably, PRMT1 affected ovarian cancer metastasis via an asymmetric methylation of BRD4." (PMID 37737256, 2023). "Based on our gene expression analyses of the L-ARG/NO module and up-regulation of PRMT1/5/ARG1/2, we hypothesized that the pathogenesis and pathophysiology of ovarian cancer might be associated with systemic and circulating changes in SDMA and L-ARG metabolites." (PMID 37684587, 2023). "It is typically expressed in various ovarian cancer cells, such as ES2 and SKOV3, and has been found to methylate FAM98A, a novel substrate of PRMT1." (PMID 38326807, 2024). "The results showed that PRMT1 and BRD4 are markedly overexpressed in ovarian cancer tissues compared to normal tissues." (PMID 37737256, 2023). "In summary, we demonstrated that PRMT1-mediated asymmetric methylation of BRD4 methylation at R179/181/183 promotes BRD4 phosphorylation and induces ovarian cancer migration and invasion." (PMID 37737256, 2023). "PRMT5, PRMT1, DDAH1, DDAH2, NOS2, ARG1, and ARG2 were all found to be up-regulated in the stage I/II or stage III/IV ovarian cancer tissues compared to normal tissues." (PMID 37684587, 2023). "Notably, gene clusters of PRMT1/PRMT5 and DDAH1/DDAH2/ARG2 persisted, while other gene tree relationships and expression significances differed between the two comparisons: normal tissue versus stage I/II ovarian cancer and stage I/II versus stage III/IV ovarian cancer." (PMID 37684587, 2023).
breast tumor (10 papers, 2016 to 2024). "Despite the detection of PRMT1-v1, v2 and v3 isoforms in breast tumor tissue, it seems that only the predominant PRMT1-v1 variant is correlated with clinical parameters such as histological grade." (PMID 34833023, 2021). "Splicing analysis has revealed that PRMT1 expression is associated with alternative splicing disorders in breast tumor samples, and mass spectrometry-based proteomics on BC patient-derived xenograft (PDX) tumors has revealed that PRMT1 substrates include proteins involved in RNA processing." (PMID 39201539, 2024). "Inhibiting PRMT1 activity has been shown to hinder the growth of solid tumors such as lung tumors, ovarian cancers, and hematological and breast tumors." (PMID 39201539, 2024). "Protein arginine methyltransferases (PRMTs), particularly PRMT5 and PRMT1 identified in our study, are overexpressed in various cancers, including ovarian, lung, multiple myeloma, and breast tumors." (PMID 37684587, 2023). "Various studies have shown that PRMT1 gene expression is higher in breast tumor samples than in healthy tissue suggesting the involvement of PRMT1 in breast carcinogenesis." (PMID 34833023, 2021). "Altogether, our results indicate that both PRMT1 mRNA and protein levels are higher in breast tumors compared to normal breast tissues, suggesting that PRMT1 could be targeted in BC." (PMID 35053470, 2022). "Moreover, we observed substantial staining of PRMT1 in the stroma of breast tumors as compared to the normal tissues." (PMID 35053470, 2022). "PRMT1 methylates BRCA1 on R610 residue in BC cell lines and in breast tumors, influencing its transcriptional cofactor functions." (PMID 39201539, 2024). "PRMT1-mediated SRSF1 methylation is important in regulating alternative splicing of genes that are known to be oncogenic, such as AURKA and RAD1, both highly expressed in breast tumor samples." (PMID 39201539, 2024). "As mRNA and protein levels do not always coincide, we studied PRMT1 protein expression in breast tumors and normal tissues using a commercial PRMT1 antibody." (PMID 35053470, 2022). "Here, the results highlight the potential of PRMT1 as a clinical molecular target to modulate BRCA1 functions after IR and suggest that pharmacological inhibition of this protein or the use of hypomethylating treatments could be therapeutically useful for sensitizing breast tumors to radiotherapy." (PMID 32764667, 2020).
melanoma (10 papers, 2021 to 2025). A malignant, usually aggressive tumor composed of atypical, neoplastic melanocytes. "In preclinical models of PDAC and melanoma, PRMT1 inhibitors combined with anti-PD-1 or anti-PD-L1 antibodies increased CD8+ T cell infiltration, suppressed tumor growth, and partially reversed resistance to ICB therapy." (PMID 41204384, 2025). "Tao reported that PRMT1 acts as an inhibitor of CD8+ T-cell recruitment and activation in melanoma and that deletion of PRMT1 reduces the abundance of H3K27ac and H4R3me2a in the Dnmt1 enhancer region, thereby reducing Dnmt1 expression in melanoma cells." (PMID 40858547, 2025). "Recently, inhibition of PRMT1 in combination with PD-1 immune checkpoint blockers has shown promising results in the treatment of melanoma." (PMID 36152748, 2022). "The increased ArgMet levels found in cancer cells are in line with overexpression of PRMT1 in human melanoma, breast, and prostate cancer." (PMID 35475236, 2021). "PRMT1 has also been found to be overexpressed in human melanoma, and PRMT1 may regulate tumor growth and metastasis by targeting activated leukocyte cell adhesion molecule (ALCAM)." (PMID 35311114, 2022). "Thus, inhibitors of the encoded proteins of PRMT1 and PMRT5 could be used in combination treatments with anti-PD-1 therapy in melanoma." (PMID 35013211, 2022). "It was suggested that targeting Axin1 stability by post-translational modifications like phosphorylation by GSK-3β, PARsylation by tankyrase-1/2 (TNKS1/2), methylation by protein arginine methyltransferase 1 (PRMT1), and SUMOylation could sensitize melanoma cells to TRAIL-based therapies." (PMID 34577571, 2021). "PRMT1 inhibition combined with anti-PD-1 therapy enhances CD8+ T cell responses and suppresses melanoma growth." (PMID 41204384, 2025). "Collaborative research by the Luo and Liu teams has revealed a novel function for PRMT1 in modulating CD8+ T cell infiltration and activation within the melanoma tumor microenvironment." (PMID 41256732, 2025). "The small‐molecule PRMT1 inhibitor DCPT1061 significantly increased the number and cytotoxic activity of tumor‐infiltrating CD8+ T cells, suppressed tumor growth, and sensitized treatment‐resistant melanomas to anti‐PD‐1 therapy." (PMID 41256732, 2025). "Moreover, PRMT1 inhibitors can remodel the tumor microenvironment by augmenting the quantity and functionality of CD8+ T cells, suppressing tumor proliferation, and restoring the efficacy of PD‐1 checkpoint blockade in resistant melanoma." (PMID 41256732, 2025).
multiple myeloma (10 papers, 2023 to 2025). "Beyond cell cycle control, PRMT1 also drives the progression and drug resistance of multiple myeloma by modulating key pathways involved in cell cycle regulation, apoptosis, and immune evasion." (PMID 41256732, 2025). "Accordingly, pharmacological inhibition of PRMT1 with compounds such as MS023 directly eliminates multiple myeloma cells and synergizes with immunotherapy, presenting a novel therapeutic strategy for refractory disease." (PMID 41256732, 2025). "To evaluate the functions of PRMT1 in multiple myeloma (MM) cells, we generated inducible knockout MM cell lines using the CRISPR/Cas9 system." (PMID 37600810, 2023). "Furthermore, we examined transcriptomic data from MM patients obtained from the Multiple Myeloma Research Foundation CoMMpass study and found that PRMT1 is expressed at significantly higher levels than the other members." (PMID 37600810, 2023). "We are the first to show the direct link of PRMT1 in multiple myeloma." (PMID 37600810, 2023).